TNC (tenascin C)
Diseases named in the same sentence as TNC in open-access papers (continued):
Sharing a sentence is not in itself a finding about the gene and the disease.
ovarian carcinoma (15 papers, 1999 to 2025). A malignant neoplasm originating from the surface ovarian epithelium. "For example, a study suggested that transforming growth factor beta-induced (TGFBI) protein and tenascin C secreted by macrophages promote the progression of ovarian cancer." (PMID 36766725, 2023). "Although serum level of tenascin-C is elevated in ovarian cancer patients, its predictive or prognostic role on survival in epithelial ovarian cancer patients seems to be not conclusive." (PMID 26090390, 2015). "In the present study we identified TGFBI, TNC, and FN1 as potential mediators of TAM-induced ovarian cancer migration, underscoring the known role of ECM proteins in tumor progression." (PMID 32312959, 2020). "In ovarian cancer cell line expressions of transforming growth factor beta 1 (TGFB1) and TNC are significantly related." (PMID 26313571, 2015). "A subsequent study in a murine ovarian carcinoma xenograft model, found that bone marrow derived MSCs engrafted at the tumour expressed CAF markers fibroblast activation protein, fibroblast specific protein 1, α-SMA and tenascin C (TN-C)." (PMID 28148268, 2017). "For example, analysis of Tenascin-C serum levels in breast and ovarian cancer did not reveal any correlations to the overall-survival or clinical data." (PMID 26967391, 2016). "In ovarian cancer, all of the up-regulated genes were increased with more advanced stage (CXCL10, RIPK2 and SPP1) or higher pathological grade (CXCL11, KPNA2, RSAD2, THOC4 and TNC)." (PMID 23536776, 2013). "Several genes found in our analysis have previously been described as biomarkers of ovarian cancer or potential therapeutic targets, including genes from the ITGA and ITGB superfamily, laminins, fibroblast growth factors, collagens, insulin growth factors, EGFR, FN1, EPHA2, TNC, SPP1, and VTN." (PMID 36352420, 2022).
Arthritis (13 papers, 2007 to 2024). Inflammation of a joint. "Tenascin-C was initially identified as a toll-like receptor 4 (TLR4) agonist that mediates the sustained local inflammatory response associated with arthritic joint disease." (PMID 29137117, 2017). "CD4+T cells specific for citrullinated tenascin-C were the most frequently observed among the progressors, and their frequencies diminished during follow-up that is, closer to arthritis onset." (PMID 39557489, 2024). "They observed higher levels of tenascin-C in the synovium affected by arthritis compared to normal synovium." (PMID 39114190, 2024). "Emerging evidence suggests the involvement of TNC in cartilage development and degeneration in arthritis." (PMID 38819423, 2024). "The expression of fibronectin and tenascin-C isoforms at sites of arthritis opens new biomolecular avenues for the treatment of arthritic conditions." (PMID 17261171, 2007). "Furthermore, tenascin-C expression was increased before and after arthritis onset, whereas periostin expression trended to increase only after arthritis onset in AIA rats ankles." (PMID 34956224, 2021). "Staining with anti-FBG antibodies was observed in synovial biopsies from people with joint inflammation; tenascin-C levels were higher in people with early RA, compared with people who had joint inflammation that spontaneously resolved and who did not develop RA, or patients with established RA." (PMID 30552174, 2019). "However, the LPS receptor TLR4, has been linked to animal models of arthritis, perhaps because of the activation of TLR4 by endogenous ligands, such as Tenascin-C." (PMID 22551352, 2012).
atherosclerosis (13 papers, 2010 to 2025). A disease characterized by the build-up of fatty material and calcium deposition in the arterial wall resulting in partial or complete occlusion of the arterial lumen. "A number of cytokines, including TNFα, induce the extracellular matrix glycoprotein, TNC, associated with the pathogenesis of atherosclerosis and foam cell formation." (PMID 31969876, 2019). "Here we report the identification of isoDGR motifs in human atherosclerotic plaque components including extracellular matrix (ECM) proteins fibronectin and tenascin C, which have been strongly implicated in human atherosclerosis." (PMID 28720870, 2017). "Accordingly, monocyte-macrophage adhesion to ECM proteins was significantly enhanced upon NGR deamidation of the atherosclerosis-associated matrix components fibronectin and tenascin C via a mechanism that required integrin αvβ3." (PMID 28720870, 2017). "Since Tenascin-C and Thrombospondin-1 are associated with sleep bruxism, atherosclerosis, and cardiovascular diseases may be a potential consequence of SB." (PMID 41010873, 2025). "Taken together, these data demonstrate that FN and TNC are closely linked with the pathology of atherosclerosis and may represent promising targets for clinical interventions." (PMID 28720870, 2017). "Numerous studies have demonstrated that tenascin-c plays an important role in the progression of atherosclerosis." (PMID 41010873, 2025). "Knockout of TNC also exacerbated the systemic inflammatory response and atherosclerosis by enhancing eotaxin (also named CCL11) levels in apoE-/- mice." (PMID 38164188, 2024). "These evidence indicate that during the pathological processes of atherosclerosis, tenascin-C expression is persistent, where its expression correlates with inflammation and plaque evolution." (PMID 35493201, 2022). "Many studies have shown that TNC plays a key role in atherosclerosis." (PMID 38164188, 2024). "TNC, especially its C domain/isoform (TNC-C), is strongly overexpressed in atherosclerotic plaque active areas but virtually undetectable in most normal adult tissues, suggesting that TNC is a promising delivery vector target for atherosclerosis-targeted drugs." (PMID 38164188, 2024). "In addition, studies should evaluate the pathophysiological and molecular mechanisms of tenascin-C and alarin in atherosclerosis, which may inform on novel therapeutic directions to manage T2DM complications and morbidities." (PMID 35493201, 2022). "Tenascin C (TNC), a rich glycoprotein of the extracellular matrix, exhibits a pro-atherosclerosis or anti-atherosclerosis effect depending on its location." (PMID 38164188, 2024). "Tenascin C has recently been identified as a TLR-4 ligand with relevance in chronicity of inflammatory arthritis and given the similarities between RA and atherosclerosis, may also be relevant in atherosclerosis." (PMID 20652007, 2010). "However, knockout of TNC not only did not change the lipoprotein profile but also the adhesion, migration, and proliferation of SMCs 37, suggesting that the effect of TNC on atherosclerosis was independent of lipid metabolism and SMCs." (PMID 38164188, 2024).
colon carcinoma (13 papers, 2012 to 2023). "It is reported that the high expression of a molecular variant of TNC was elevated depending on a malignant potential in the stroma of some malignancies, including oral cancer, sarcoma, breast cancer, and colon cancer." (PMID 28106752, 2017). "A study on human colon carcinoma tissue demonstrated a link between Tenascin-C upregulation and cancer cell invasion." (PMID 32560557, 2020). "We identified that BGN, S100A8, S100A9, and TNC expression levels were elevated significantly in colon cancer samples." (PMID 32050430, 2020). "TNC (tenascin C) was responsible for invasion of colon cancer cells but was important for metastasis and angiogenesis in EOC." (PMID 30970615, 2019). "In this study, we showed that TNC participated in the malignant transformation of colon cancer cells through one of its functional components, TNIIIA2." (PMID 28106752, 2017). "The increased expression of TNC has been reported in both inflammatory bowel disease patients and colon cancer patients." (PMID 28106752, 2017). "In this study, we found that colon cancer cell invasion and metastasis was accelerated by TNC/TNIIIA2 via MMP induction." (PMID 28106752, 2017). "A mechanistic study showed that TNC promotes colon carcinoma cell invasion via the epidermal growth factor receptor (EGFR) and hepatocyte growth factor (HGF) signaling pathways; TNC secreted by CAFs activates EGFR and HGF." (PMID 22481923, 2012). "Additionally, TNC has been shown to have an important role in actin cytoskeleton remodeling by the inhibition of RhoA activation in human colon cancer cells." (PMID 36765641, 2023). "In addition, we found that Tenascin-C was abundantly secreted by the colon cancer cells with high metastatic potential, and highly expressed in lymph nodes with metastasis." (PMID 27191989, 2016). "In addition, our results showed that Tenascin-C was abundantly secreted by the colon cancer cells with high metastatic potential, and highly expressed in lymph nodes with metastasis." (PMID 27191989, 2016). "Thus, a new therapeutic strategy for colon cancer could target TNC/TNIIIA2, and further investigation is needed." (PMID 28106752, 2017). "TNC-mediated inhibition of proliferation was abolished in both cell lines after PTP1B inhibition, while NF-κB inhibition was effective only in colon cancer cells." (PMID 37963919, 2023). "We have previously shown the GC-sensitive and GR-regulated release of several pro-angiogenic factors (TNC, TGFβ and HGF/SF) by cultured colon cancer-derived myofibroblasts." (PMID 27717848, 2017). "In this study, we investigated the effect of TNC/TNIIIA2 on the invasion and metastasis of colon cancer cells, Colon26-M3.1, or PMF-Ko14, using an in vitro and in vivo experimental system." (PMID 28106752, 2017). "The results showed that the expression levels of S100A9 and TNC in colon carcinoma tissues were not correlated with age or gender (P > 0.05), but correlated with TNM stages and metastasis (P < 0.05)." (PMID 27191989, 2016).
Obesity (13 papers, 2016 to 2025). Accumulation of substantial excess body fat. "Subsequently tenascin-C has also been implicated in the chronic low-grade inflammation associated with obesity." (PMID 29137117, 2017). "In contrast, among the genes interacting with key adipogenic factors, LPXN, TNC, THBS1, and OGG1 have been directly associated with obesity and fat accumulation." (PMID 40130165, 2025). "RNA sequencing of tumors identified tenascin C (TNC) as a candidate obesity-related serum tissue environment marker with elevated expression in tumors of HFD-fed mice." (PMID 38797735, 2024). "We observed similar results, with OPN, YKL-40 and TNC levels being significantly increased (P<0.01) by obesity and cancer." (PMID 27612200, 2016). "In this study, we constructed a co-expression network between obesity and PTC and identified four common hub genes (MNDA, TNC, CHIT1, MMP9) and two common TFs (ELF4, STAT3), which might provide new diagnostic and therapeutic strategies for obesity-related PTC." (PMID 37671970, 2023). "The extracellular glycoprotein TNC is a member of damage-associated molecular pattern proteins which play important roles in ECM remodeling, a key process in adipose tissue expansion and obesity." (PMID 28932870, 2018). "Therefore, an influence of obesity in CC development via the ECM proteins OPN, YKL-40 and TNC can be inferred representing promising diagnostic markers or target molecules for therapeutics." (PMID 27612200, 2016). "Our results indicate that in the GSE44000 obesity-related dataset, the expression levels of MNDA, TNC, CHIT1, and MMP9 exhibited significant differences." (PMID 37671970, 2023). "Tenascin C is also related to activation of the toll-like receptor 4 (TLR4) signaling pathway, which triggers the obesity-induced inflammatory response." (PMID 32485856, 2020). "In conclusion, these four genes (MNDA, TNC, CHIT1, MMP9) may serve as a link between obesity and PTC and should be further examined in subsequent analyses." (PMID 37671970, 2023). "Based on our findings, it can be concluded that these four genes (MNDA, TNC, CHIT1, and MMP9) may have important biological roles in preventing and treating obesity and PTC." (PMID 37671970, 2023). "Certain factors, including obesity and drug use, which are thought to affect tenascin-C levels, could not have been isolated from the study." (PMID 39114190, 2024).
bladder cancer (12 papers, 2007 to 2025). "Elevated levels of the extracellular glycoprotein tenascin C correlate with poor prognosis in multiple cancer types including breast and bladder cancer as well as being associated with increased invasiveness." (PMID 27058757, 2016). "Among these identified genes, 5 genes (CALD1, HOXB3, HOXB6, MOGAT2, and TNC) have been reported to be associated with the development or prognosis of bladder cancer, indicating that the results in our study are consistent with previous publications in bladder cancer." (PMID 33204728, 2020). "Different in terms of protein functions, such as Hepatocyte growth factor activator inhibitor type 1 (HAI-1), Stathmin 1 (STMN-1) and Tenascin C (TN-C), whose activity has been observed in various types of cancer, inspired us to study them in bladder cancer." (PMID 40507426, 2025). "In bladder cancer, tenascin-C, an extracellular matrix glycoprotein and potential therapeutic target, has been revealed to characterize the preparation of lymph nodes before the arrival of tumor cells." (PMID 36835583, 2023). "In this study, we evaluate tenascin-C as a marker of pre-metastatic niche formation in bladder cancer patient lymph nodes." (PMID 34564696, 2021). "When the fibroblasts were exposed to conditioned medium from J82 bladder cancer cells for 72 h, they showed strong tenascin-C protein expression; interestingly, expression of α-SMA remained unaffected." (PMID 34564696, 2021). "Bladder cancer EVs induced tenascin-C expression in fibroblasts in an NF-κB-dependent manner." (PMID 34564696, 2021). "Tenascin-C expression in regional lymph nodes may be a good predictor of bladder cancer metastasis and an appropriate imaging target." (PMID 34564696, 2021). "Finally, we report the effects of bladder cancer EVs on primary fibroblast tenascin-C expression in vitro." (PMID 34564696, 2021). "These authors showed that Tenascin-C is upregulated in the benign lymph nodes of lymph node metastasis-positive bladder cancer patients and that bladder cancer-derived EVs might induce premetastatic niche formation in lymph nodes by directly targeting tenascin-C." (PMID 36674900, 2023). "On the other hand, three genes (LAMC2, TNC, and SETD5) were found related to the survival of bladder cancer in grade 2 carcinoma." (PMID 32640634, 2020).
diabetes (12 papers, 2017 to 2024). "Increasing number of 100–140 μm elements at a 2–3mm distance from the orifice, seeming to originate from shrinkage of originally μm units, is caused by diabetes in TNC KO mice (Fig. 6yellow and green symbols, red spots)." (PMID 39076867, 2023). "Recent studies have demonstrated that higher TNC expression in cardiactissue and its presence in plasma are associated with worse outcomes in patientswith diabetes, however the role of TNC is still unknown." (PMID 39076867, 2023). "The TNC gene was also annotated to a locus we detected; this gene has been demonstrated to be highly associated with a wide range of diseases related to inflammation, including diabetes." (PMID 36864386, 2023). "Ishikawa reported high expression of periostin and tenascin-C in the trabecular meshwork of patients with diabetes." (PMID 39768583, 2024). "TNC KO mice with diabetes showed afurther elevation in the number of ring units in the 100–140 μm,while it was significantly reduced in the 140–220 μm ranges(p < 0.001 with the χ2 test)." (PMID 39076867, 2023). "Tenascin C has an established role in the cardiomyocyte adhesion process and is defined as a marker in diabetes." (PMID 34830471, 2021). "Additionalinvestigations should reveal whether TNC KO mice are similarly protected againstcardiac microvascular endothelial dysfunction in diabetes." (PMID 39076867, 2023). "For instance, in patients with diabetes, relevant alterations in circulating Tenascin-C, MMP-9, ET-1 or NGAL could be observed." (PMID 32545310, 2020). "TNC is a member of ECM, and ECM remodeling has been shown to occur in diabetes and insulin resistance models." (PMID 35493201, 2022). "Blood flow should cover larger distances indiabetic networks, but interestingly STZ-induced diabetes did not generatefurther geometrical changes in TNC KO mice." (PMID 39076867, 2023). "The prognosis of patients with AIS at 90-days after IVT was used as the dependent variable, and age, smoking, hypertension, diabetes, coronary artery disease, hyperlipidemia, atrial fibrillation, IL-6, MMP-9, ADAMTS13, TRX, TNC, and GSN were considered independent variables." (PMID 36127663, 2022). "However, diabetes failed to induce dramaticchanges in TNC KO mice (yellow lines)." (PMID 39076867, 2023). "Most surprisingly, STZ-induceddiabetes did not induce further geometrical changes in TNC KO mice, suggestingthat the re-expression of TNC in diabetes may constitute a key signaling moleculein the development of microvascular dysfunction in small coronary arteries." (PMID 39076867, 2023).
fibrosis (12 papers, 2016 to 2025). the formation of excess fibrous connective tissue in an organ or tissue in a reparative or reactive process. "Using the CCl4-induced model, we found that TNC overexpression in the livers of CCl4-induced mice paralleled fibrosis progression, while loss of TNC expression in Tnc KO mice largely attenuated liver fibrosis." (PMID 41214839, 2025). "Since TNC deficiency significantly increased the severity of acute kidney injury after IR, which made the association between TNC and fibrosis more complicated, we investigated the role of TNC in fibrosis and explored the mechanism using UUO model." (PMID 36522320, 2022). "Our immunohistochemical analysis of liver tissue samples from cirrhosis patients and fibrosis-free patients also confirmed the increased expression of the TNC protein in fibrosis patients." (PMID 41214839, 2025). "The inhibition of TNC has been demonstrated to attenuate cardiac fibrosis and cardiomyocyte apoptosis after MI, suggesting the involvement of TNC in the pathology of cardiac dysfunction after MI." (PMID 36980863, 2023). "Both periostin and TNC bind to each other and also co-localize in subepithelial fibrosis in asthmatic patients." (PMID 30473714, 2018). "POSTN is directly attached to collagen type I, V, fibronectin, tenascin-C, and POSTN itself and this complex assists in subepithelial fibrosis and tissue remodeling." (PMID 30061580, 2018). "Fibrosis is a complex condition mediated by profibrotic factors, an imbalance of collagen synthesis and degradation, upregulation of the extracellular matrix including POSTN and TNC, and increased oxidative stress." (PMID 30186543, 2018).
heart failure (11 papers, 2013 to 2024). Inability of the heart to pump blood at an adequate rate to meet tissue metabolic requirements. "The expression of proteins involved in Ig-mediated immune activation [e.g., Fc Gamma Receptor IIIa FCGR3A], proteins associated with heart failure [e.g., Tenascin C (TNC), Quiescin sulfhydryl oxidase 1 (QSOX1)], was enhanced in severe MIS-C compared to KD." (PMID 39457139, 2024). "Tenascin-C (TN-C) was also another peptide found in the serum of heart failure patients and suggested using it to predict ventricular remodeling and poor prognosis." (PMID 35127880, 2021). "Levosimendan, which increases the calcium sensitivity of TnC-Ca2+, has been proven to improve myocardial contractility and to treat heart failure." (PMID 35126176, 2021).